CTSL (cathepsin L)
Diseases named in the same sentence as CTSL in open-access papers (continued):
Sharing a sentence is not in itself a finding about the gene and the disease.
tumor (continued). "In order to evaluate cathepsin L as a potential target in cancer therapies, it will be crucial to establish its role in each type of cancer and stage of tumor progression." (PMID 25927437, 2015). "It is possible that the contributing role of cathepsin L to the regulation of angiogenesis depends on the timing, and the extent of the blood supply coverage in the particular tumor type." (PMID 25927437, 2015). "Deletion of cathepsin L in Myc-driven PNET significantly increased tumor cell death, and was more apparent during the late stages of tumor progression." (PMID 25927437, 2015). "In recent studies, cathepsin L and S were considered to be effectively controlled targets of tumor cells, because they play key roles in the invasion and migration of tumor cells." (PMID 25889816, 2015). "high CTSL expression was significantly correlated with advanced clinical staging, histological grade and tumor recurrence." (PMID 25384089, 2014). "Tumor formation assay in nude mice was used to analyze the effect of CTSL on the tumorigenicity of MHCC-97H cells." (PMID 25384089, 2014). "Early experimental studies revealed that the metastatic capability of tumor cells was correlated with CTSL activity." (PMID 25384089, 2014). "CTSL plays a major role in antigen processing, tumor invasion and metastasis, bone resorption, and turnover of intracellular and secreted proteins involved in growth regulation." (PMID 25384089, 2014). "Increased expression of cathepsin L, a target gene involved in retrograde signaling, is an important factor in the invasive behavior of tumor cells." (PMID 23418583, 2013). "We used a combined approach to screen potent cathepsin L inhibitors that promised to emerge as important leads in cancer research owing to the role that cathepsin L plays during tumor development and metastasis." (PMID 24564425, 2013). "Other studies have found that inhibition of cathepsin L significantly reduced tumor invasion and proliferation, increased cell death, and prevented resistance to chemotherapy in animal models." (PMID 23049944, 2012). "As concerns cathepsin L, this belongs to the cysteine protease family and its expression was suggested to correlate with increased invasion ability of tumor cells, e.g. of M14 murine melanoma cells in vitro." (PMID 20684763, 2010). "The expression levels of the lysosomal papain-like cysteine proteases cathepsin-B (Cath-B) and cathepsin-L (Cath-L) are frequently strongly elevated in tumours of diverse origin." (PMID 14562034, 2003). "In vitro experiments also confirmed that reduced CTSL expression inhibited tumour growth." (PMID 39893643, 2025). "CTSL was significantly upregulated in tumour tissues compared with normal tissues in both datasets." (PMID 41261048, 2025). "One notable example is gallinamide A, a modified tetrapeptide that acts as a potent and selective inhibitor of the cysteine protease cathepsin L. Cathepsin L is often overexpressed or secreted by cancer cells to degrade extracellular matrix components, facilitating tumor invasion and metastasis." (PMID 40559642, 2025). "Given that CTSL has been associated with aggressive tumour phenotypes and poor prognosis in various cancers, our study suggests that the USP20‐STUB1‐CTSL axis may serve as a potential biomarker and therapeutic target in HNSCC." (PMID 41261048, 2025). "Knockout of CTSL restores the tumour‐suppressive function lost upon KDM4C depletion." (PMID 41261048, 2025). "On the contrary, CTSL has a wider range of substrates than CTSB81 and has been implicated in several physiological and pathological processes including bone remodelling, angiogenesis and tumour invasion." (PMID 37417221, 2024). "Moreover, previous studies reported that cathepsin L can promote tumour cell proliferation by activating CCAAT-displacement protein/cut homeobox (CDP/Cux) transcription factors and accelerating entry into the S phase of the cell cycle." (PMID 38921586, 2024).
tumor (continued). "Our research suggested that tumor immunity may be closely related to the CTSL signature for HNSCC patients." (PMID 37292206, 2023). "Furthermore, it has been demonstrated that many cancer cells secrete cathepsin-L into the extracellular milieu, where it plays a role in tumor invasion and metastasis." (PMID 37047535, 2023). "In conclusion, our findings suggest that CTSL may play an important role in the uptake of SARS-CoV-2 in most of the tumor tissues." (PMID 35414771, 2022). "Thus, it is important to predict the susceptibility of cancer patients for SARS-CoV-2 entry and the disease outcome by accessing the expression of CTSL in different tumor tissues." (PMID 35414771, 2022). "CTSL promoted tumor angiogenesis by regulating the CDP/Cux/VEGF-D pathway." (PMID 35647031, 2022). "Likewise, knockout of the lysosomal cathepsin L gene (CtsL) in mice exacerbates tumor growth in the epidermis of mice expressing the human papillomavirus oncogene K14–HPV16." (PMID 35326559, 2022). "In addition, a subcutaneous tumor xenografts model in M-NSG mice was used to assess tumor response to CTSL inhibition in vivo." (PMID 36133820, 2022). "The ectodomain of EpCAM and CTSL are both secreted into the tumor micro-environment of cancer patients, whereby EpCAM could possibly inhibit CTSL activity." (PMID 34209658, 2021). "EpCAM mutations could potentially serve as a biomarker of increased CTSL activity in the tumor microenvironment and identify patients that would benefit from protease inhibitors targeting CTSL." (PMID 33980181, 2021). "In contrast, the inhibition of cathepsin S was shown to convert regulatory T lymphocytes from immunosuppressive to immunostimulatory cells and inhibition of cathepsin L enhanced cytotoxicity of CD8+ T cells in the co-culture model of tumour cells and myeloid-derived suppressor cells." (PMID 34948293, 2021). "Interestingly, both EpCAM and CTSL are known to be secreted into the tumor microenvironment and are present in the serum of human cancer patients." (PMID 33980181, 2021). "In this study, we first showed that CTSL plays a facilitative role in regulating tumor angiogenesis of GC and that it could serve as an independent prognostic indicator and therapeutic target for GC." (PMID 32388635, 2020). "Furthermore, cathepsin L transforms inactive heparanase-1 form into active heparanase-1, both trigger extracellular matrix remodeling, which contributes to enhanced tumor-host interaction of the tumor." (PMID 33053017, 2020). "Cathepsin L is produced and secreted by both tumor cell and macrophage populations." (PMID 31565189, 2019). "Furthermore, the activity of CTSL+B and CTSB showed a significant association with tumor stage and lymph node involvement in GBC patients." (PMID 31824841, 2019). "In addition, cathepsin L shRNA knockdown studies revealed that cathepsin L from both the tumor cell and the macrophage population is important for tumor cell invasion." (PMID 31565189, 2019). "Having established the diagnostic and prognostic significance of CTSL and CTSB overexpression in the tumor tissues of GBC, it was of interest to investigate if the levels of these cathepsins in serum could accurately discern GBC patients from controls." (PMID 31824841, 2019). "Additionally, silencing CTSL can prevent the drug resistance of tumor cells, reduce the proliferation of ovarian cancer cells, weaken the cell invasion and migration properties, and increase the sensitivity of cells to paclitaxel." (PMID 31370861, 2019).
tumor (continued). "Similarly, intense staining of CTSL in tumor endothelial cells was also noted in 55% (22/40) of GBC patients as compared to only 20% (12/60) in endothelial cells of controls, indicating a remarkable increase in CTSL levels in GBC (p < 0.0001)." (PMID 31824841, 2019). "CTSL plays an important role in tumor occurrence, development, and metastasis." (PMID 31370861, 2019). "Moreover, our study further verified that CTSL expression level was significantly higher in tumor tissues than in adjacent tissues, and positively related to the tumor grade." (PMID 30732622, 2019). "Inhibition of CTSL may enhanced the effect of paclitaxel or cisplatin to inhibit the growth of tumor, especially for those patients with drug resistance." (PMID 31370861, 2019). "Besides, we have also indicated that expression of CTSL correlates with radioresistant, as well as malignant grades of tumor tissues." (PMID 30732622, 2019). "It is unclear whether the mechanisms regulating CTSL-mediated resistance to paclitaxel and cisplatin in other tumor cells is consistent with the mechanisms of drug resistance in A549 cells." (PMID 31370861, 2019). "Furthermore, genetic knockdown of cathepsin L in either tumor cells or macrophages reduces tumor cell invasion in Boyden chambers." (PMID 31565189, 2019). "However, in contrast to cathepsins B and S that are present in both stromal cells, such as macrophages, and tumor cells, cathepsin L is primarily secreted by tumor cells." (PMID 29719685, 2018). "In addition, the level of cathepsin L expression correlates positively with the degree of malignancy in metastatic tumor development because cell detachment can be partly explained by cathepsin L-mediated cleavage of E-cadherin." (PMID 29560748, 2018). "In certain tumours cathepsin L is massively upregulated, thus promoting the malignancy of tumours." (PMID 29044689, 2018). "Thus, we measured the levels of cathepsin L in tumor tissue by IHC analysis and Western blot analysis." (PMID 29221112, 2017). "Downregulation of NudCD1 in tumor cells that showed a high expression of the protein resulted in a down-regulation of some oncogenic genes such as CTSL, MMP15, uPAR, VEGF, COX-2, S100A4, MUC1, MDM2 and RAC110 and an increase of the resistance to 5-fluorouracil-induced apoptosis." (PMID 29021621, 2017). "However, co-administration of 3-MA abrogated the effects of KSP on the upregulation of cathepsin L protein in tumor tissue." (PMID 29221112, 2017). "We investigated the effect of CTSL knockdown on tumor invasion and migration." (PMID 27351223, 2016). "We suggest that FOXO3a and cathepsin L may be potential therapeutic targets for blocking tumor metastasis." (PMID 27127880, 2016). "Finally, we knocked down cathepsin L using an shRNA to confirm the mechanism of FOXO3a's tumor-promoting function." (PMID 27127880, 2016). "Thus, genetic blockade of cathepsin L activity is inferred to retard Myc-driven tumor growth, encouraging the potential utility of pharmacological inhibitors of cysteine cathepsins in treating late stage tumors." (PMID 25927437, 2015). "However, tumor cell-supplied cathepsin L appears to function intracellularly, as suggested by this study and others." (PMID 25927437, 2015). "However, the mechanism by which cathepsin L modulates tumor progression is highly context-dependent and remains controversial." (PMID 25927437, 2015). "Motivated by the recent implication of cysteine protease cathepsin L as a potential target for anti-cancer drug development, we used a conditional MycERTAM;Bcl-xL model of pancreatic neuroendocrine tumorigenesis (PNET) to assess the role of cathepsin L in Myc-induced tumor progression." (PMID 25927437, 2015). "The expression level of CTSL mRNA is significantly higher in tumor tissues." (PMID 25384089, 2014).
tumor (continued). "Our study suggests that high level of CTSL expression might be positively correlated with worse tumor biological features, such as rapid tumor progression and metastases, and that CTSL plays an important role in the development and progression of HCC." (PMID 25384089, 2014). "This difference may be due to the ability of cathepsin-L to degrade extracellular matrix allowing for more tumor growth in those tumors expressing high levels of cathepsin-L." (PMID 24474939, 2013). "In these previous studies, sets of genes associated with pathways such as apoptosis (e.g., bax, bcl-2), DNA damage repair (e.g., Ku80, GADD45, XRCC5), cell adhesion (e.g., ICAM-3), angiogenesis (e.g., HIF-1a), and tumor cell invasion (e.g., CTSL, CTSB) were identified." (PMID 20184742, 2010). "Since metastasis depends upon both the invasiveness and migration of tumor cells, cathepsin L may be a therapeutic target of strong clinical interest." (PMID 17488522, 2007). "Moreover, acidosis activates cathepsin L, an enzyme that converts plasminogen into plasmin, which in turn degrades extracellular matrix proteins and activates matrix metalloproteinases, facilitating tumor invasion." (PMID 40223032, 2025). "Therefore, CTSL may influence immune responses by regulating immune cell functions or altering the tumour microenvironment." (PMID 39893643, 2025). "Additionally, CTSL plays a crucial role in tumor biology, particularly in the processes of invasion and metastasis by degrading the extracellular matrix and basement membrane, thus promoting tumor cell invasion and dissemination." (PMID 40226717, 2024). "Furthermore, combination of CTSL inhibition and chemotherapy potently blocked tumor growth in vivo." (PMID 36133820, 2022). "Besides, increased CTSL expression was positively associated with advanced tumor stages, though there was no statistical significance." (PMID 36133820, 2022). "Furthermore, CTSL released by carcinoma cells has been shown to produce the angiogenesis inhibitor endostatin from collagen XVIII, raising the possibility that CTSL could act as a putative tumor suppressor by inhibiting angiogenesis." (PMID 33919392, 2021). "In addition, we further identified the tumor-promoting effect of CTSL in vivo." (PMID 32388635, 2020). "Furthermore, cathepsin L was co-expressed with heparanase-1 and transformed inactive heparanase-1 form into active heparanase-1, triggering extracellular matrix remodeling, which contributes to enhanced tumor-host interaction of the tumor." (PMID 33053017, 2020). "Thus, CTSL is a novel target for reducing tumor progression." (PMID 27351223, 2016). "Furthermore, cathepsin L expression was limited to the insulin-producing cells in the tumor tissue, indicating a beta-cell origin of cathepsin L expression in the MycERTAM;Bcl-xL tumor model." (PMID 25927437, 2015). "Altogether, this study show that the first evidences of the expression and clinical significance of CTSL in HCC, suggesting that CTSL might involve in the development of HCC as a tumor promoter, and thereby may serve as a valuable prognostic marker for HCC patients." (PMID 25384089, 2014). "Additionally, the incidence of CTSL protein expression in well-differentiated carcinoma was significantly lower than that in poor-differentiated tumors, and CTSL expression was significantly related with tumor differentiation (P = 0.007)." (PMID 25384089, 2014). "Altogether, the aberrantly expressed signature genes (XRCC4, CTSL, CTSD, and HSPA8) is closely related to tumor malignant progression." (PMID 41399382, 2026). "To further validate the upregulation of CTSL at the protein level, we performed Western blot analysis on five paired HNSCC tumour and adjacent normal tissues." (PMID 41261048, 2025). "The co-enrichment of CTSL and CTSB, in conjunction with elevated NRP1 levels, contributes significantly to angiogenesis and tumor invasion, marking the progression from a healthy state to the development of ccRCC." (PMID 40134439, 2025).
tumor (continued). "Given that Diclofenac has been previously reported by our group and others as an anti‐tumour agent in HNSCC,23, 27 we investigated its potential role in regulating CTSL stability." (PMID 41261048, 2025). "To investigate the expression pattern of CTSL in HNSCC, we first analysed its mRNA levels in tumour versus normal tissues using TCGA and GSE178537 datasets." (PMID 41261048, 2025). "TGF-β, VEGFA were known to promote tumor-cell EMT and metastasis, respectively, and secreted cathepsins such as Cathepsin L and Cathepsin B were reported to facilitate tumor-cell invasion." (PMID 38926796, 2024). "The expression of Cathepsin L is significantly elevated in the cancer nests of BCC and SCC compared to normal tissue, with particularly notable increases in expression at the tumor margins." (PMID 39312365, 2024). "In particular cathepsin B (CTSB), L (CTSL), and S (CTSS) are used as targets for near-infrared (NIR) fluorescence imaging (FI), a technique that allows real-time intraoperative tumor visualization and resection margin assessment." (PMID 39331316, 2024). "Recent studies show that targeting CTSL activity increases CD8 + T cell toxicity, while inhibiting CTSX restores tumor cell invasion." (PMID 39736788, 2024). "TAMs secrete CTSB, CTSL, and CTSS and therefore, TAMs also provoke tumor growth, angiogenesis, invasion, and metastasis responses." (PMID 36289617, 2022). "We developed tumor spheroids for parental and resistant Y79 cells, and we observed high ZEB1 and cathepsin L expression in resistant spheroids using immunofluorescence." (PMID 36291907, 2022). "Previous studies reported that the up-regulation of CTSL or PTX expression correlates with poor prognosis as well as lymph node or distant metastases, tumor stage, and overall survival in HNSCC." (PMID 34680330, 2021). "We discovered that the protein levels of HNRNPK, P4HA1, and TUBA4A were significantly upregulated, while CTSL, HNRNPK, and OSBPL5 were significantly downregulated in the tumor tissues compared to those of normal tissues." (PMID 35284334, 2021). "Tumor type-specific deviations in ACE2/protease co-expression were less prominent for CTSB, CTSL, and FURIN compared to TMPRSS." (PMID 33707526, 2021). "To determine if aging affects molecular determinants of muscle wasting in our models, we measured the expression of the atrogenes Fbxo32, Trim63, Foxo3a, and Cathepsin-L in skeletal muscle of young and old LLC and C26 tumor cell injected mice." (PMID 35008253, 2021). "Among these cysteine proteinases, lysosomal CTSB, CTSD, CTSL, and CTSS have been shown to be involved in tumor malignant progression and are potential targets of anti-tumor therapy." (PMID 34923982, 2021). "The function of cathepsin L (CTSL), an endosomal proteolytic enzyme, in promoting tumor metastasis is well recognized." (PMID 32388635, 2020). "Lysosomal cysteine cathepsins (CTSL and CTSB) are degradative enzymes playing a pivotal role in tumor invasion and metastasis." (PMID 31824841, 2019). "The enzymatic activity of CTSL and CTSB was assayed in tumor and control gallbladder tissues using a synthetic fluorogenic substrate CBZ-PheArg-NMec and expressed as RFU/min/mg protein." (PMID 31824841, 2019). "Higher levels and altered localization of cysteine cathepsins, including CTSL and CTSB within the tumor microenvironment, are essential for tumor growth, invasion, and neovascularization." (PMID 31824841, 2019). "Tumor specimens from 53 patients with NSCLC and Xenograft models was also utilized to explore the regulatory relationship of CTSL, TGF-β, Egr-1 and CREB." (PMID 31370861, 2019). "Cinobufagin significantly improved β-END synthesis by increasing the expression of POMC, CTSL and stimulated the release of β-END by raising the levels of inflammatory chemokines in the tumor and adjacent tissues." (PMID 28002791, 2017).